IRF1 (interferon regulatory factor 1)
Diseases named in the same sentence as IRF1 in open-access papers (continued):
Sharing a sentence is not in itself a finding about the gene and the disease.
infection (continued). "Increased RNA expression levels of the ISGs Mx2, Rsad2, and USP-18 mRNA were found in both WT and IRF-1−/− 2 days post infection, followed by a decline." (PMID 24675692, 2014). "Viral burden from the peripheral organs i.e. liver, spleen and lungs was higher in IRF-1−/− mice in comparison to WT mice 2 days post infection." (PMID 24675692, 2014). "Interferon regulatory factor 1 (IRF1) is induced by HIV early in the infection process and serves two functions: transactivation of the HIV-1 genome and thus replication, and eliciting antiviral innate immune responses." (PMID 23799084, 2013). "Viperin can be induced in an IFN independent manner via IFN regulatory factor-1 (IRF-1), following infection with the RNA virus, vesicular stomatis virus (VSV)." (PMID 23638199, 2013). "After 24 hours of infection, this strain induced significantly less IRF1 protein than a Pru strain (p<0.001) and PruΔgra15 infected cells have similar IRF1 levels as cells infected with RH(I) and CEP(III) strains which possess inactive copies of GRA15." (PMID 23240025, 2012). "We first blotted for IRF1 as a control to confirm that infection with any of these strains inhibited the IFNγ induced accumulation of IRF1, as we have shown by immunofluorescence." (PMID 23240025, 2012). "Of all the ISGs, IRF1 demonstrated the most robust inhibition (infection percentage >11 SD below the mean in the control cells), and did so independently of ZAP overexpression; in both cell types less than 5% of the cells became infected." (PMID 22615998, 2012). "After two hours of infection with either RH or RHΔrop16 parasites, HFFs were subsequently stimulated with IFNγ for two hours, cells were fixed and permeabilized, and IRF1 expression and STAT1 tyrosine phosphorylation were visualized." (PMID 23240025, 2012). "Interferon-γ, the strongest inducer of IRF-1, is thought to be a key player in the control of pre-erythrocytic and blood stage infection, both in rodent malaria infections and in human malaria infections." (PMID 21867552, 2011). "IRF-1-/- mice were vulnerable to lethal infection with enhanced viremia, increased viral replication in peripheral tissues, altered tropism, and rapid dissemination into the CNS." (PMID 21909274, 2011). "Although fewer CD8+ T cells were observed in naïve animals, WNV-specific CD8+ T cells rapidly expanded in IRF-1-/- mice and retained the capacity to clear infection." (PMID 21909274, 2011). "Ex vivo analysis revealed a cell-type specific antiviral role as IRF-1-/- macrophages supported enhanced WNV replication but infection was unaltered in IRF-1-/- fibroblasts." (PMID 21909274, 2011). "Leukocytes were recovered from the brains of wild type and IRF-1-/- mice at day 8 post-infection after perfusion." (PMID 21909274, 2011). "Cytokines like CCL5, small inducible cytokine A2, IL8 and other immune responsive genes like STAT1, IRF1 and B2 M were found to be up-regulated at this time point post infection with seasonal influenza virus." (PMID 21439068, 2011). "For example, 5 to 10-fold higher levels of type I IFN activity were observed in IRF-1-/- mice at day 3 after infection (P<0.001)." (PMID 21909274, 2011). "A predominant Th1 immune response was observed during infection, as 6 of 11 investigated Th1 associated genes, including TNF, IFNG, and some IFNG-signaling responsive genes (SOCS1, STAT1, WARS and IRF1), were strongly up-regulated at 24 hpi and/or 48 hpi." (PMID 18811943, 2008). "However, the levels of other innate immune signaling proteins, such as JAK1, STAT1, p-STAT1, IRF3, or IRF1, remained similar after infection with UL88-STOP or WT TB40/E." (PMID 40638072, 2025). "Additionally, the expression of interferon regulatory factor-1 (IRF-1) is reduced post-infection, impacting the regulation of various innate and adaptive immune responses." (PMID 39902829, 2025).
infection (continued). "Knockdown of Snhg15 during VEEV TC-83 infection resulted in the suppression of ten genes including Irf1, Junb, Atf3, Relb, Pim1, Hbegf, Ccl5, Ankrd33b, and H2-K2, all of which were also increased during TC-83 infection when the expression of Snhg15 increased in primary mouse astrocytes." (PMID 40463150, 2025). "Furthermore, IRF1 plays a critical role in regulating the acute infection of murine gammaherpesvirus 68 (MHV68) and the establishment of chronic infection." (PMID 40586041, 2025). "The central function of IFNγ is to augment the immune response upon infection with nonviral pathogens, and IRF1 deficiency in macrophages causes severe mycobacterial, but not viral, disease in humans." (PMID 39773901, 2025). "This basal IRF1 expression could also have a role in controlling HSV-1 infection during the early stages of infection." (PMID 40586041, 2025). "Moreover, IRF1 expression was diminished in Ifnar1–/– pBMDMs following MPXV infection, indicating that IRF1 functions downstream of type I IFN signaling." (PMID 41225161, 2025). "IRF1 could inhibit the mechanistic target of rapamycin (mTOR)/p70 S6 kinase (p70 S6K) cascade to suppress Mtb-infection in macrophages." (PMID 38625657, 2024). "Moreover, this upregulation was partially dependent on ZBP1, as KO macrophages exhibited reduced IRF-1 protein level 16 hours post-infection." (PMID 39850894, 2024). "In contrast, some other IRFs, including IRF1, are transcriptionally induced during infection." (PMID 37622993, 2023). "Moreover, in poly (I: C)-treated IPEC-J2 cells, overexpression of Npro or infection with wtCSFV not only down-regulated the production and the promoter activity of IRF1 significantly but also inhibited IRF1 nuclear translocation." (PMID 37090696, 2023). "IRF-1 repression was recently shown to exacerbate and extend MHV-68-mediated germinal center expansion during the early stages of infection, and decreased IRF1 expression is associated with gamma-herpesvirus associated posttransplant lymphoproliferative disorder in humans." (PMID 36298850, 2022). "We tested whether reexpression of IRF1 from a doxycycline‐inducible construct could reduce the infection levels (Fig EV5B and C)." (PMID 35852463, 2022). "On day nine post infection, analysis of tissue homogenates from distal organs (liver, spleen and mesenteric lymph nodes (mLNs)) indicated only low systemic pathogen spread in controls, while Irf1–/– mice displayed high systemic C. rodentium dissemination." (PMID 36175404, 2022). "Because immunohistochemical stainings demonstrated a profound increase in colonic IRF-1 protein during C. rodentium infection, we took advantage of this widely utilized model to establish cell type specific functions of IRF-1 during infections with extracellular, noninvasive enteric pathogens." (PMID 36175404, 2022). "This may explain the observation in this study that expression of IRF7 in KO IFNAR1 cells promotes the expression of IFIT5 and IRF1 at the later stage of infection." (PMID 35891486, 2022). "Indeed, IRF1 overexpression in differentiated Irf1 KO significantly lowered infection rates and viral titers." (PMID 35852463, 2022). "Still, this is somewhat at odds with our observation of a markedly stronger overall expression of IRF1 upon RVFV infection, which may be due to complex feedback mechanisms." (PMID 34685580, 2021). "Whether induced in response to infection or basally expressed, the impact of IRF1 on innate immunity stems from its capacity to drive gene expression." (PMID 33476326, 2021). "Therefore, to specifically address the contribution of TBK1 to IRF1 induction we performed siRNA-mediated knockdown of TBK1 in MDMs prior to infection with HMPV." (PMID 34248923, 2021). "Therefore, we tested if type I and also type III IFNs contribute to IRF1 induction in HMPV-infection by activating IFNAR or IFNLR." (PMID 34248923, 2021).
infection (continued). "Thus, it seems plausible that IRF1 has continued to evolve to allow more rapid responses to infection by pathogens." (PMID 33476326, 2021). "Using this approach, we found three ISGs that restricted infection: IRF1, TRIM31, and RARRES3." (PMID 34871166, 2021). "Indeed, a genetic deficiency in IFN-gamma or IRF1 (in IFN-gamma/or IRF1/mice) and the pharmacological inhibition of IDO leads to massive mortality in mice a few days after acute infection with Toxoplasma gondii." (PMID 32784805, 2020). "In the circRNA-miRNA-mRNA network, circRNAs would indirectly regulate 25 chicken mRNAs, such as STAT1/4 and IRF1/7, indicating that these circRNAs might play a critical role in regulating vvIBDV-infection." (PMID 33076825, 2020). "However, infection with wtCSFV or Npro overexpression led not only to significant reduction of IRF1 expression and its promoter activity in poly(I:C)-treated IPEC-J2 cells but also to blockage of IRF1 nuclear translocation." (PMID 31683525, 2019). "The products of IRF1 also trigger an interferon response during early infection." (PMID 31412766, 2019). "As shown, SH0165 infection of 3D4/21 cells significantly upregulated IRF1." (PMID 31766159, 2019). "IFNβ at 0.1 ng/ml protected both parent and IRF1 KO BEAS-2B cells from VSV-GFP infection." (PMID 31156620, 2019). "It is likely, therefore, that whether the IFN-dependent or -independent functions of IRF1 are relevant to viral defense depends upon cell type, the viral pathogen, infectious dose, and duration of infection." (PMID 31156620, 2019). "Correspondingly, interferon regulatory factor 1 (IRF1) which is an essential regulator of immune responses and inflammation against infection, was found increased but with a constant expression level from the beginning of the infection till it reaches severity." (PMID 31614626, 2019). "We found that the mRNA of IRF1 was also downregulated with the infection of FCV." (PMID 30009167, 2018). "Since overexpression of fe-IRF1 can inhibit the proliferation of FCV F9, we wanted to know whether infection with FCV can induce the expression of IRF1." (PMID 30009167, 2018). "The study sought to establish whether the infection of HGEC with live P. gingivalis would affect the mRNA expression of various genes potentially implicated in EGF signaling, mainly SOCS-3, IRF-1, EGF, EFGR, and STAT-3." (PMID 28748038, 2017). "Thus, we first monitored the nuclear translocation of NF-κB (phospho-p65) and IRF-1 4 hours to 3 days post Mav infection of human primary macrophages using confocal microscopy." (PMID 28806745, 2017). "Our data showed that IRF1 mRNA was expressed at a low basal level in PK-15 cells, and was induced rapidly after poly(I:C) treatment at very considerable levels at 6 hours post infection (hpi) and reached to the peak at 24 hpi (72-fold versus control)." (PMID 26593937, 2015). "Notably, IRF1 knockdown was incomplete and the reduced amount of IRF1 protein observed upon infection with RSV-HD infected si-1 treated cells likely explains the low level of expression of IFNL1 observed upon infection of the knockdown cells." (PMID 26336095, 2015). "As IRF1 is a transcription factor critical for IFNγ signaling by driving downstream expression of many IFNγ target genes, we also assessed if knock down of IRF1 in M-CSF-treated and M-CSF/IFNγ-treated macrophages altered infection of EBOV GP/rVSV in peritoneal macrophages." (PMID 26562011, 2015). "We also demonstrated that knockdown of IRF1 could modestly rescue EBOV GP/rVSV infection in peritoneal macrophages that were stimulated with IFNγ." (PMID 26562011, 2015). "Moreover, the inhibition of IRF-1 causes a decrease in IPNV-induced apoptosis and delayed expression of PSR in IRF-1 knockdown cells during infection." (PMID 25342322, 2014). "We first tested whether our system was responsive to infection with Ad-IRF-1 using the ISRE WT construct and performed RT-PCR to determine whether we could detect a stable GFP-containing message." (PMID 24650050, 2014).
infection (continued). "While IRF-1−/− mice succumb to i.n. infection, all mice survive the infection by i.v. route." (PMID 24675692, 2014). "While IRF-1 did not obviously play a role in induction of type IFN, activation of adaptive immune cells and viral spread through the brain, we found that IRF-1 induces an intrinsic antiviral response, which is pivotal to control revive of viral replication at later stages of the infection." (PMID 24675692, 2014). "Therefore, for infection to persist, the effects of IRF1 and probably other ISGs should be inhibited in infected cells." (PMID 25414701, 2014). "To confirm our hypothesis we determined IRF-1 expression in peripheral organs and the different brain parts during the course of infection." (PMID 24675692, 2014). "To examine the impact of IRF-1 during brain infection more carefully, we dissected the mouse brain into four parts, i.e. olfactory bulb, cerebrum, cerebellum and brain stem post infection and determined their viral load by plaque assay at different time points." (PMID 24675692, 2014). "However, expression levels increased again on day 6 post infection in IRF-1−/− mice, which correlates to IFN-β induction." (PMID 24675692, 2014). "In addition, immunohistological analysis of infected IRF-1−/− brains revealed an effective infection of VSV-eGFP in neurons." (PMID 24675692, 2014). "However, significant amounts of IFN-β were found only in the cerebrum and cerebellum of IRF-1−/− mice, 6 days post infection." (PMID 24675692, 2014). "Similarly, expression of several genes in the canonical IFN signaling pathway, including Ifng, Jak2, Stat1, Stat2, Socs1, Irf1, Irf9, Tap1, Ifitm1, Psmb8, Ifi35, Gas1 and Fit3 were up-regulated during infection by the mutant strain." (PMID 25201772, 2014). "We next asked whether pre-infection could also enhance IFNγ-induced STAT1 binding to labeled gamma-activated sequence (GAS) oligonucleotides from the Irf-1 promoter in an electrophoretic mobility shift assay (EMSA)." (PMID 23527309, 2013). "Infection of human dendritic cells with L. major activated IRF-1 resulting in IL-12 production." (PMID 22724038, 2012). "To begin to define the cellular pathways and/or gene products that inhibit S. flexneri replication in MEFs, we first tested whether IRF1 is induced by IFNγ during infection and whether IRF1 contributes to IFNγ-mediated restriction of this bacterium." (PMID 22912573, 2012). "Additionally, Pru(II) infection alone led to the induction of IRF1 protein, in concordance with previous immunofluorescence experiments." (PMID 23240025, 2012). "However, increased replication was observed at 48 and 72 hours after infection in IRF-1-/- Mφ when compared to wild type cells (2.5-fold, P = 0.02 and 7.4-fold, P = 0.001, respectively)." (PMID 21909274, 2011). "In particular, the function of IRF-1 in the context of infection by WNV or other flaviviruses remained unknown." (PMID 21909274, 2011). "We therefore hypothesized that IRF-1 might contribute to the systemic levels of IFN-αβ in circulation after infection." (PMID 21909274, 2011). "However, this response is not sufficient to compensate for increased viral replication in peripheral tissues, which results in early and enhanced infection in the CNS of IRF-1-/- mice." (PMID 21909274, 2011). "These included chemokine ligand IP-10 and genes controlled by pro-inflammatory cytokines TNF-α, IL-1β, IFN-γ; namely, interferon regulatory factor 1, Cd274 antigen, metallothionein 2, proteasome subunit (Psmb9), and tumor necrosis factor Tnfsf10 were progressively up-regulated after infection." (PMID 20082697, 2010). "Consistent with STAT1 and STAT2 activation, they also observed an increased abundance of genes encoding downstream targets of interferon signalling in response to infection, including the interferon regulatory factor 1 gene, located in the 5q31q33 chromosomal region." (PMID 20657648, 2010).
infection (continued). "Interestingly, although IRF1 expression was decreased upon depletion of CARINH or Carinh in isolated macrophages, total IRF1 expression was unchanged in whole lungs of infected mice at day 4 post-infection, suggesting redundant mechanisms of IRF1 gene regulation at later stages of infection." (PMID 39773901, 2025). "Indeed, the computed top DEG, typifying each cluster on day 3 in the effector phase of infection, hosted several interferon-induced anti-viral genes (Irf1, Irf7, Ifrd1, Socs1, Socs3, Ifit1, Bst2, and Isg15) as well as genes associated with mature resident Trm cells (Cd69, Nfkbid, Brd2, FosB)." (PMID 35260804, 2022). "At a later stage of infection, it was shown that genes involved in the major histocompatibility complex I (MHC-I) pathway were substantially downregulated, and the downregulation of interferon regulatory factor 1 (irf1) has been implicated to mediate this response." (PMID 36090977, 2022). "Infection with wtCSFV inhibited IRF1 nuclear translocation induced by poly(I:C) stimulation while ∆Npro did not inhibit such translocation, indicating that Npro might be involved in blocking IRF1 nuclear translocation." (PMID 31683525, 2019). "Thus, to explore whether IRF1 also directly regulates the JAK/STAT signaling pathway, we asked if exogenous IFNs differentially affects infection of IRF1 KO and parent cells with VSV, a pathogen that is highly sensitive to exogenous type I and III IFNs." (PMID 31156620, 2019). "From the results of three independent experiments, we found that the inability to undergo autophagy during infection led to higher expression of many pro-inflammatory genes as compared to autophagy-competent cells, including established ISGs, such as Psmb10, Cd274, Cxcl10, Irf1 and Tap1." (PMID 29748576, 2018). "Moreover, lipoteichoic acids of S. aureus induce TLR2 signalling which leads to IRF1 upregulation and therefore also might contribute to the growth arrest during infection." (PMID 27834866, 2016). "The induction of IRF1 by RelA may be a primitive and pivotal event in response to infection." (PMID 26460486, 2015). "However, IRF-1−/− mice displayed higher IFN-α in the serum 2 days post infection." (PMID 24675692, 2014). "Thus, in both brain parts, cerebellum and cerebrum, loss of IRF-1 leads to higher viral replication in the later phase of infection although IFN-β is expressed, indicating its non-redundant function in mediating antiviral activity." (PMID 24675692, 2014). "In the Pumwani cohort, specific polymorphisms in IRF1 were shown to result in reduced IFNγ-stimulated IRF-1 protein expression and were associated with resistance to infection, but not altered disease progression, suggesting that the protective effect is limited to early events in HIV infection." (PMID 24257114, 2013). "We identify the antiviral transcription factor IRF1 as a direct target of the circadian transcription factor BMAL1, resulting in rhythmic expression of a basal antiviral gene program prior to infection." (PMID 42182353, 2026). "IRF1 also regulates the expression of key components necessary for NLRP3 and AIM2 activation after infection, including ZBP1 and guanylate-binding proteins." (PMID 40018047, 2025). "We found that both IRF1 and GBP5 reduced infection in NHSK-1-VP30s, demonstrating that the EBOV-inhibitory capabilities of these ISGs extends to human keratinocytes." (PMID 41472248, 2025). "In summary, this study identifies IRF1 and GBP6 as 2 key loci at which infection-induced systemic inflammation leads to epigenetic changes that are conserved from HSPCs to downstream monocytes, providing a mechanistic avenue for central trained immunity." (PMID 41364527, 2025). "We individually altered the expression levels of IRF1, GATA1, and Bcl11b 24 h post-infection with ALV-J." (PMID 40075948, 2025).